MCF2L2 (MCF.2 cell line derived transforming sequence-like 2)
Description:
Probably functions as a guanine nucleotide exchange factor.
Synonyms: ARHGEF22; KIAA0861
Tractability: PROTAC: ubiquitination databases record sites on it.
Gene: Protein-coding gene on chromosome 3 (183,178,041 to 183,428,778, reverse strand). Ensembl gene ENSG00000053524.
Subcellular location (Human Protein Atlas): Centriolar satellite; Cytosol
Gene Ontology:
Molecular function: guanyl-nucleotide exchange factor activity
Cellular component: cytoplasm; cytosol
Genetic constraint (gnomAD): Loss-of-function variants: 73 observed, 109.69 expected, observed/expected ratio (o/e) 0.67, 90% interval 0.55 to 0.81. The upper end of that interval is the gene's LOEUF score, 0.81, which puts it in group 3 of 6, group 1 being the genes least tolerant of losing a copy. Missense variants: 1,075 observed, 1,205 expected, observed/expected ratio (o/e) 0.89, 90% interval 0.85 to 0.94. Synonymous variants: 405 observed, 446.32 expected, observed/expected ratio (o/e) 0.91, 90% interval 0.84 to 0.99.
Homologues: Orthologues: chimpanzee MCF2L2 (99% identical), macaque MCF2L2 (97% identical), dog MCF2L2 (78% identical), pig MCF2L2 (74% identical), rabbit MCF2L2 (61% identical), tropical clawed frog mcf2l2 (52% identical), zebrafish mcf2l2 (49% identical). Paralogues in human: MCF2L (42% identical), MCF2 (33% identical), TRIO (20% identical), KALRN (19% identical), PLEKHG4B (16% identical), TIAM2 (15% identical), PLEKHG4 (14% identical), TIAM1 (14% identical), ARHGEF40 (13% identical), SPATA13 (12% identical), ARHGEF7 (11% identical), SESTD1 (11% identical), and 10 more.
Diseases named in the same sentence as MCF2L2 in open-access papers:
MCF2L2 is named in the same sentence as 4 diseases in open-access papers, as found by Europe PMC text mining. Sharing a sentence is not in itself a finding about the gene and the disease. The quoted sentences say what the papers report.
type 1 diabetes (2 papers, 2010 to 2021). "IGF2 plays a key role in glucose metabolism, HSPB6 is associated with insulin resistance, and MCF2L2 is related to type 1 diabetes and polycystic ovary syndrome." (PMID 34645493, 2021). "IGF2 plays a key role in glucose metabolism, HSPB6 might be associated with insulin resistance, and MCF2L2 might be one of the most important marker genes contributing to type 1 diabetes and polycystic ovary syndrome." (PMID 34645493, 2021).
diabetic nephropathy (1 paper, 2010). "MCF2L2, ADIPOQ and SOX2 genes are located in chromosome 3q26-27, which is linked to diabetic nephropathy (DN)." (PMID 20667095, 2010).
MCF2L2 also shares sentences with these, for which no sentence is quoted: Insulin resistance (1 paper); polycystic ovary syndrome (1).